IL6 (interleukin 6)
Diseases named in the same sentence as IL6 in open-access papers (continued):
Sharing a sentence is not in itself a finding about the gene and the disease.
depression (continued). "IL-6 and TNF-α may also compromise the blood–brain barrier in depression." (PMID 38541828, 2024). "In conclusion, acute hyper-hypoxia can regulate the IL-6-PGC1α-MFN2 signaling pathway, aggravate inflammation, influence mitochondrial biogenesis and fusion, damage hippocampal neurons, reduce cognition, memory, and emotional regulation, and accelerate the occurrence and development of depression." (PMID 39135980, 2024). "One study reported a significant increase in the serum levels of TNF-α, IL-1β and IL-6 in patients with AD and depression, compared to AD patients without depression, with strong inverse correlations between the MMSE scores and pro-inflammatory cytokine levels." (PMID 39526037, 2024). "A randomised-controlled trial of patients with major depressive disorder found greater improvements in depression symptoms following exercise intervention in those with higher IL-6 at baseline, whilst no changes were found in the inflammatory biomarkers before and after the intervention." (PMID 38699297, 2024). "Furthermore, in a larger study with 249 healthy controls, 108 MS patients without depression, and 42 patients with MS and depression; serum IL-6 was highest in those with MS and depression." (PMID 38304427, 2024). "Finally, improving depression scores did not alter the biochemical parameters of gut inflammation, including serum IL-6, CRP, or fecal calprotectin levels." (PMID 38839073, 2024). "The main question is whether plasma concentrations of pro-inflammatory cytokines (IL-6, IL-1α, and TNF-α) can serve as predictive biomarkers for depression severity and whether these concentrations are modulated by gender among patients diagnosed with major depressive disorder (MDD)." (PMID 39595067, 2024). "The effect of IL6-stressor interactions on the amygdala was not shown in this study, but the expression of IL-6 might be dampened in the amygdala, which might partially contribute to the blunted affect of depression." (PMID 37324818, 2023). "The commonly reported biomarkers of depression include serum corticosterone levels (cortisol levels in humans) to assess the involvement of the HPA axis, pro-inflammatory cytokines (TNF-alpha, IL-1, and IL-6), brain-derived neurotrophic factor (BDNF), and neurotransmitters (5-HT, DA, NE, and GABA)." (PMID 36986112, 2023). "Thus, IL-6, TNF-α and IFN-γ might represent important biomarkers for targeted treatments in schizophrenia and depression might represent an inflammatory endophenotype of schizophrenia with potential responsiveness to immune-based therapies." (PMID 37723153, 2023). "However, no respectable difference in the IL-6 levels was observed in patients with cancer alone or cancer with depression." (PMID 37153524, 2023). "Notably, MSCs have the ability to downregulate the expression of the proinflammatory cytokines IL-1β, IL-6, and TNF-α, which is one of the major reasons that contribute to the development of depression, as discussed in the cytokine hypothesis." (PMID 36986674, 2023). "Elevated IL-6 may lead to HPA axis dysfunction, altered synaptic neurotransmission, and reduced neurotrophic factors, which are indirectly involved in the pathogenesis of depression." (PMID 37692389, 2023). "However, there has been little evidence about the role of anti-IL-6 effect of FLV in treating depression." (PMID 37304432, 2023). "Another study revealed that IL-6 levels were inversely related to cognitive levels, and acupuncture could reduce IL-6 levels in the PFC and reduce anxiety and depression in PTSD model animals." (PMID 37200784, 2023). "IL-6 and its downstream impact on TNF-α, and IFN-γ, could offer novel targets for treatment if offered at the relevant phenotypic profile including those with depression." (PMID 37723153, 2023).
depression (continued). "In the clinical treatment of COPD complicated with anxiety and depression, BIPAP boasts effective amelioration of lung function and relief of anxiety and depression symptoms, and its mechanism of action may have a close bearing on ameliorating the levels of 5-HT, NKA, and IL-6 in patients." (PMID 37680802, 2023). "High levels of pro-inflammatory cytokines, such as IL-6, CRP, cortisol, and cerebral white matter lesions in patients with depression and frailty may adversely affect each other, leading to an increased risk of cerebrovascular disease, decreased activities of daily living, and mortality." (PMID 36780484, 2023). "Besides RA, IL-6, IL-17, and TNF-α also increase in malignancy conditions, including colorectal cancer, breast cancer, and pancreatic cancer, which implicates the pathogenesis of anxiety and depression." (PMID 37916198, 2023). "Previous studies in depression have found that CRP in serum/plasma is correlated with both CRP in the cerebrospinal fluid (CSF) and CSF pro-inflammatory cytokines, and that blood CRP, IL-6 and neutrophils levels are correlated with dysconnectivity of a brain functional network." (PMID 37264010, 2023). "Given that NEGR1 is considered one of the major etiological factors of multiple mental illnesses, including major depressive disorder and autism, our findings may provide new insight into understanding the role of NEGR1 and IL-6 during the development of these neuropathological symptoms." (PMID 37187893, 2023). "Proinflammatory cytokines (including interleukin-1, interleukin-6, and tumor necrosis factor-α), growth factors such as vascular endothelial growth factor (VEGF), and NF-kB activation are all mediated through the AGE-RAGE signaling pathway, which promotes the onset and severity of depression." (PMID 37745719, 2023). "Finally, a negative association between interleukin-6 (IL-6) and Rosenberg Self-Esteem Scale (Beta=-0.019, p=0.019) and a positive association between TNF-α and the Center for Epidemiologic Studies Depression Scale Revised (Beta=0.003, p=0.015) were found." (PMID 37529617, 2023). "Since the correlation of IL-6 diurnal index with BDI-II depression was still relatively significant, we proceeded to an exploratory path analysis on possible pathways from BLA activity to the IL-6 diurnal index and BDI-II depression under the rs1800796 × NLC interaction." (PMID 37324818, 2023). "Studies have shown that inflammatory factors IL-1β, IL-6, TNF-α, and CRP are elevated and anti-inflammatory factors IL-4, IL-8, and IL-10 are decreased in peripheral and cerebrospinal fluid and correlate with patients’ symptoms and disease duration in depression and anxiety." (PMID 36624089, 2023). "It has also been suggested that depression is an inflammatory disorder characterized by increased levels of proinflammatory cytokines such as tumor necrosis factor (TNF), interleukin-1β (IL-1β), and IL-6 in several brain regions, and similar findings have been reported in experimental studies." (PMID 36185078, 2022). "Pro-inflammatory cytokines, e.g., IL-1β, IL-6, TNF-α, and acute phase proteins, were described to be increased in experimental animal models of chronic stress-induced depression as well as in patients with major depressive disorder (MDD) compared to healthy controls." (PMID 36014842, 2022). "Furthermore, the upregulation and downregulation of IL6 and CRP affect depression severity." (PMID 36009493, 2022). "Furthermore, patients with major depressive disorder have elevated concentrations of IL–6 in their plasma when compared with people without depression." (PMID 35682430, 2022). "Omega-3 fatty acids are protective against depression in older men by decreasing C-reactive protein (CRP) levels, while the total intake of fat, saturated fatty acids (SFA), and monounsaturated fatty acids (MUFA) exerted an increased effect on both CRP and interleukin (IL)-6 in older women." (PMID 36615742, 2022).
depression (continued). "However, there was evidence for an association of a genetically-predicted effect of IL-6 activity on CRP levels with smoking (ORIL-6/CRP–Smk = 1.06 (1.03–1.09), p < 0.001, but not depression (ORIL–6/CRP-Dep = 0.93 (0.85–1.02), p = 0.126." (PMID 36057695, 2022). "However, TNF-α, IL-1B, and IL-6 secretion in DD group was significantly enhanced than that in depression and diabetes group (P < 0.05, P < 0.01); CX3CR1 blocker treatment of DD group significantly reduced the levels of TNF-α, IL-1B, and IL-6 in hippocampus of all groups (P < 0.05, P < 0.01)." (PMID 36072409, 2022). "However, whether imbalances between IL-6 and TGF-β and between Th17 and Treg occur in depression and whether depression can be improved upon restoring these imbalances are unknown." (PMID 36430328, 2022). "However, the relationship between cognitive behavioral therapy (CBT), IL-6 and depression has not yet been established." (PMID 35633813, 2022). "first reported the association of cytokine polymorphisms with PSD, showing that patients with polymorphisms of anti-inflammatory cytokines IL-4 and IL-10 rather than pro-inflammatory cytokines TNF-α, IL-1β, IL-6 and IL-8 had an increased propensity to develop depression in the acute phase of stroke." (PMID 36225923, 2022). "A combination of elevated IL-6, TNF-α, and CRP provided preferable prediction performance in terms of AUC (0.83) over individual biomarkers, with considerable sensitivity (78.5%) and specificity (77.9%) for depression, but it demanded higher costs and additional time." (PMID 35757220, 2022). "However, in patients with a PSDD, IL-6 levels did not change after the acute period, remaining constant, while in patients without a depressive disorder, this parameter decreased by 30 days after IS." (PMID 36547090, 2022). "The subjects of this study were FDD patients who did not take medication, suggesting that changes in serum IL-6 and IL-17 levels have been manifested in the early stages of depressive disorder, and IL-17 is closely related to the severity of depressive disorder." (PMID 35615531, 2022). "Overactivation of inflammatory responses and increased levels of inflammatory mediators like interleukin (IL)−1β, IL‐6, tumor necrosis factor alpha (TNF‐α), the acute phase reactant (CRP), and high mobility group box 1 (HMGB1) were seen in both patients and rodents with depressive disorder." (PMID 35089644, 2022). "Specifically, IL-6 might have a negative effect on mood, and it has been shown to be a predictor of higher severity and chronicity of depression." (PMID 34631754, 2021). "Therefore, we speculate that JTW may play a role in the treatment of DM and depression through the key targets such as INS, AKT1, IL-6, VEGF-A, TNF and so on." (PMID 34875999, 2021). "Interestingly, during a one- year study-period, serum levels of IL-6, IL-10, TNF-α, and IFN-γ were significantly higher in the post-stroke depression group relative to a control group, suggesting a relationship between immune dysregulation and post-stroke depression." (PMID 34884906, 2021). "Furthermore, we hypothesized that physical activity would decrease IL-6 and TNF-α more strongly than TAU, resulting in a stronger decrease of the depression severity." (PMID 34204400, 2021). "TNFα-levels were not related to depression scores or pain intensity, nor was IL-6." (PMID 34248700, 2021). "Similarly, light therapy of seasonal disorders to alleviate symptoms of depression did not reduce IL-6 levels." (PMID 34945157, 2021). "Similarly, IL-6 has also been identified as a strong predictor as it accounts for a substantial portion (21%) of self-reported fatigue in pwMS without depression or sleep disorders." (PMID 34589733, 2021). "More precisely, MDD had increased IL-1β, tumor necrosis factor α (TNF α), sTNFR 1, IL-12 and IL-10 while BD depression was characterised by an increase in IL-6, sTNFR 2, IL-18, IL-33, ST2, and KLOTHO." (PMID 33946871, 2021).
depression (continued). "Recently, several studies have investigated the influence of peripheral proinflammatory cytokines (e.g., IL-6, IL-1β, and TNF-α) on neuronal synaptic plasticity, neurogenesis, and neuromodulation, which play critical roles in the initiation, relapse, and progression of depression." (PMID 33466877, 2021). "There is now evidence that depression is accompanied by activation of the immune-inflammatory response system (IRS) marked by increased levels of pro-inflammatory cytokines, such as interleukin (IL)-1, IL-6, tumor necrosis factor (TNF)-α, and interferon (IFN)-γ in the blood." (PMID 33945102, 2021). "Furthermore, increased IL-6 as well as decreased interleukin-4 (IL-4) and albumin in serum discriminate MS patients with from those without depression." (PMID 34764926, 2021). "Due to the multifaceted pathogenesis of depression, this study aimed to clarify whether the KBD formula ameliorated the effect of UCMS-induced changes in expression levels of the depression-related genes BDNF, CREB, GR, SGK1, FKBP5, IL-1β, IL-6, and TNF-α." (PMID 34358084, 2021). "A recent study suggested the possible antidepressant effects of the Mediterranean diet, as patients with depression who followed that particular type of diet showed no increases in IL-6 levels, whereas participants that did not follow a Mediterranean diet showed a larger increase." (PMID 33578686, 2021). "In the respondents, IL-6 levels significantly decreased after 8 weeks of treatment (p = 0.029), while no such changes were observed in patients with no improvement in the clinical symptoms of depression." (PMID 33920992, 2021). "Increased levels of proinflammatory biomarkers (including CRP, IL-6, and TNF-α) were found in patients with depression, whereas NSAIDs treatment significantly inhibited the inflammatory response and reduced the suicidal ideation and depression symptoms in depressed patients." (PMID 32522211, 2020). "Hypoxia induces mood changes mediated by inflammation and increased IL-6, CRP and other inflammatory markers that may impair mood, similarly to increased IL-6, IL-8 and TNF-α in individuals with a mood disorder such as bipolar and depression." (PMID 33255790, 2020). "Bivariate Pearson’s correlations table between IL-6 and IL-1β with childhood trauma experiences, psychological outcomes, and physical outcomes among participants with and without clinically significant depression." (PMID 32413063, 2020). "Moreover, the MI+ depression model also exhibited similar results to those of the IM group in terms of echocardiography (EF and FS), cardiac markers (CK-MB and LDH), antioxidants (SOD, GSH-Px, and CAT) and inflammatory factors (CRP, IL-6, and TNF-α)." (PMID 32973539, 2020). "Similarly, in a study with 86 dementia-free women aged 70–84 years, women with current depression had higher levels of CSF IL-6 compared with those without depression." (PMID 32235786, 2020). "It has been suggested that, owing to the impact of IL-6 on hepatocytes, IL-6 may function in activating PLP phosphatase activity, thus decreasing circulating PLP concentrations, though this remains to be assessed in patients with depression." (PMID 34589848, 2020). "Clinical studies (NCT00291239; NCT03080025) are investigating the role of IL-6 as a biomarker or causative molecule in depression, but none are investigating STAT3 or oncostatin M. It should be noted that STAT3 is activated by elevated IL-6 and oncostatin M belongs to the IL-6 family." (PMID 32998701, 2020). "The cooccurrence of chronic pain and depression is intimately related to increases in TNF-α, IL-1β, and IL-6 in target structures such as the PFC, ACC, amygdala and hippocampus, emphasizing the involvement of glial activation in limbic regions involved in pain and depression processing." (PMID 32849076, 2020).
depression (continued). "Adipose tissue produces inflammatory factors, including cytokines such as IL-6, TNF-α, and chemokines, which in turn may activate widespread immune reaction, potentially leading to or exacerbating inflammation-related diseases, including depression." (PMID 32140686, 2020). "Furthermore, cancer patients with depression have been found to have higher plasma levels of IL-6 in comparison to cancer patients without depression or healthy people." (PMID 32850269, 2020). "This could mean that the correlation between pro-inflammatory cytokines (TNF-α in depressed participants, IL-6 in non-depressed participants) and cognitive fatigue symptoms may not be affected by depression." (PMID 32528052, 2020). "Elevated levels of proinflammatory cytokines, especially interleukin-1β (IL-1β), interleukin-6 (IL-6), and tumor necrosis factor alpha (TNF-α), can interact with the neuroendocrine function and influence neuronal function, which has been reported in depression." (PMID 32596383, 2020). "Although there have been several reports indicating that inflammatory factors, notably circulating IL-6 and TNF-α, were associated with major depressive illness, as previously observed, the IL-6 rs1800795 SNP was not directly related to depression scores in the present study." (PMID 30967802, 2019). "Moreover, the IL-6 SNP did not interact with childhood maltreatment or sex to predict depression symptoms." (PMID 30967802, 2019). "We found that these patients presented with different immune features in the same affective state, and IL-6 may be used for the differential diagnosis of BD and MDD, and may be especially useful in distinguishing mania/mixed and depression even when the clinical manifestations are atypical." (PMID 30762747, 2019). "Rats that show increased depression-like behaviors after neuropathic injury display higher levels of proinflammatory cytokines (e.g., IL-1β, IL-6) as well as imbalance of pro/anti-inflammatory cytokines, compared with rats without depression-like phenotype and sham-operated rats." (PMID 29876878, 2019). "Recent studies indicated that IL-6 is the most consistently elevated cytokine in the blood of MDD patients, therefore it may serve as a predictive biomarker and a potential target to treat depression in humans." (PMID 31057357, 2019). "We hypothesized that unipolar depression and bipolar depression might present with different serum levels of cytokines (IL-6 and IL-8) and CRP even in the same affective state, and that mania and depression states might also present with different serum levels of cytokines and CRP." (PMID 30762747, 2019). "IL-6 may be a driver of downstream systemic inflammation in HS inducing CRP, hepcidin and anaemia of chronic disease, immunoglobulins, Th17 differentiation, as well as contributing to other features seen in HS such as depression." (PMID 30265680, 2018). "Our hypothesis was that elderly with depression or Alzheimer’s disease had higher levels of IL-1β, IL-6, TNF-α and CRP than controls without psychiatric disorders." (PMID 30104698, 2018). "Although Asp358Ala is associated with serum IL-6 and soluble IL6R levels, it is not clear whether the effect of Asp358Ala on risks of severe depression and/or psychosis is mediated by specifically serum IL-6, soluble IL6R or membrane-bound IL6R." (PMID 29197507, 2018). "In major depression with atypical features, lowered IL-4 but increased IL-2 concentrations were observed, whereas no changes in IL-6 or TNFα concentrations could be established." (PMID 29103192, 2018). "There is relatively strong evidence that hsCRP and IL-6 are raised in unipolar depression, whereas our results suggest this is not the case in bipolar depression, although it is unclear whether this may be because of methodological differences between studies." (PMID 30113291, 2018).